ZNF670-ZNF695 (ZNF670-ZNF695 readthrough (NMD candidate))
Gene: Protein-coding gene on chromosome 1 (246,945,547 to 247,078,811, reverse strand). Ensembl gene ENSG00000135747.
Genetic constraint (gnomAD): Missense variants: 119 observed, 136.44 expected, observed/expected ratio (o/e) 0.87, 90% interval 0.75 to 1.02. Synonymous variants: 54 observed, 50.66 expected, observed/expected ratio (o/e) 1.07, 90% interval 0.86 to 1.34.